ENSG00000302686 (novel transcript)
Gene: Long non-coding RNA gene on chromosome 19 (13,834,512 to 13,836,446, forward strand). Ensembl gene ENSG00000302686.
Gene Ontology:
Biological process: miRNA-mediated post-transcriptional gene silencing
Cellular component: RISC complex